VDAC2P1 (VDAC2 pseudogene 1)
Synonyms: formerly VDAC2P
Gene: Processed pseudogene on chromosome 21 (16,094,415 to 16,095,372, reverse strand). Ensembl gene ENSG00000214976.
Diseases named in the same sentence as VDAC2P1 in open-access papers:
VDAC2P1 is named in the same sentence as 1 disease in open-access papers, as found by Europe PMC text mining. Sharing a sentence is not in itself a finding about the gene and the disease.
VDAC2P1 shares sentences with these, for which no sentence is quoted: sarcoma (1 paper).